MYC (MYC proto-oncogene, bHLH transcription factor)
Diseases named in the same sentence as MYC in open-access papers (continued):
Sharing a sentence is not in itself a finding about the gene and the disease.
B-cell lymphoma (continued). "Synchronous BCL2 and MYC translocations in double-hit high-grade B-cell lymphomas were obvious from cfTNA." (PMID 34204385, 2021). "According to the WHO classification, a total of five (17.2%) patients were, therefore, reclassified as aggressive B-cell lymphoma with MYC, BCL2, and/or BCL6 rearrangements (DHL/THL)." (PMID 34830747, 2021). "MiR-17-5p has been reported to counterbalance MYC expression and function to ensure optimal B cell lymphoma growth." (PMID 34930894, 2021). "A total of 170 patients with DLBCL and high-grade B-cell lymphoma with MYC, BCL2, and/or BCL6 rearrangements (DHL/THL), diagnosed and treated in our hospital between 2000 and 2021, were included." (PMID 34830747, 2021). "This is the case in double-expressor (DE) DLBCLs and high-grade B cell lymphomas with translocations in MYC and BCL2, also known as “double-hit lymphomas” (HGBL-DH)." (PMID 33670870, 2021). "Double hit lymphoma (DHL)/THL refer to B‐cell lymphoma with MYC accompanied with Bcl‐2 and/or Bcl‐6 gene rearrangements." (PMID 34698437, 2021). "High expression of c-MYC in B-cell lymphoma was previously shown to correlate with sensitivity towards SUMO E1 inhibition; therefore, we studied c-MYC expression in our panel of chondrosarcoma cell lines." (PMID 34359724, 2021). "Two double-hit high-grade B-cell lymphoma cases were also included, featured by simultaneous MYC and BCL2 translocations that were verified using FISH (Case 18, 19)." (PMID 34204385, 2021). "Elevated NEAT1 levels are associated with suppression of miR-34b activity and increased MYC gene expression in B-cell lymphoma cells." (PMID 34440124, 2021). "As more studies emerge, it has become evident that HIV-1 Tat can alter cellular events in complex and multiple ways, and one of the crucial events in the pathogenesis of a number of aggressive B-cell lymphomas is dysregulation of c-MYC." (PMID 34277639, 2021). "Currently, the term High-grade B-cell lymphoma with MYC and BCL2 and/or BCL6 rearrangements is used." (PMID 34945004, 2021). "Here we investigated the role of dendritic cells (DCs) for the therapeutic effect of ICB in a λ-MYC-transgenic mouse model of endogenously arising B-cell lymphoma." (PMID 33141285, 2021). "In B-cell lymphomas, MYC can directly regulate expression of the miR-17-92 gene cluster and inhibit apoptosis." (PMID 34930894, 2021). "To determine the influence of IL-6 on lymphomagenesis mediated by deregulated MYC expression, we used an Eμ-myc murine model of B cell lymphoma." (PMID 33651821, 2021). "Chromosomal rearrangements involving BCL2, BCL6 and MYC are commonly found in the most frequent B cell lymphomas, namely follicular lymphomas (FLs) and diffuse large B-cell lymphomas (DLBCLs)." (PMID 33768318, 2021). "Enforced expression of B cell lymphoma oncogenes such as MYC, NMYC or BCL2, in the B cell compartment or loss of tumor suppressors can also skew MuLV driven malignancies toward B cell lymphoma and leukemias." (PMID 34484175, 2021). "Double-hit lymphoma (DHL) is an aggressive type of B-cell non-Hodgkin lymphoma characterized by genetic translocations involving MYC and either BCL2 or BCL6, even if, rarely, all three rearrangements can occur together (triple-hit lymphoma)." (PMID 33801599, 2021). "Dysregulation of c‐MYC is essential in the pathogenesis of a number of B‐cell lymphomas, including DLBCL." (PMID 33749163, 2021). "The transcription factor MYC plays a central role in the onset and progression of several B-cell lymphomas." (PMID 34885204, 2021). "The dearth of documented consensual clinicopathological characterization of Taiwanese patients with DHL/THL, otherwise designated high-grade B-cell lymphoma (HGBL) with MYC and BCL2 and/or BCL6 rearrangements, informs the present study." (PMID 33807449, 2021).
B-cell lymphoma (continued). "MYC/BCL2/BCL6 triple-hit lymphoma (THL) is an uncommon subset of high-grade B-cell lymphoma with aggressive clinical behavior and poor prognosis." (PMID 34113336, 2021). "The other example, PRMT5, is overexpressed in some B-cell lymphoma lines in an MYC-dependent manner." (PMID 35008680, 2021). "Conversely, c-MYC translocation and detection has become essential in the clinical diagnosis and prognosis of aggressive B-cell lymphomas including BL." (PMID 34277639, 2021). "To functionally investigate the role of CXCR4 hyperactivation in the context of aggressive B-cell lymphoma, we chose the Eμ-Myc mouse model, which is characterized by B-cell-targeted overexpression of MYC, leading to MYC-driven aggressive B-cell lymphoma." (PMID 34363012, 2021). "It is especially active against aggressive MYC+/BCL2+ B cell lymphomas and this likely reflects the eIF4A-dependent translation of both MYC and BCL2." (PMID 33562682, 2021). "We also subcutaneously injected BCR-ABL (9663), RAS (3588), and the MYC-dependent B cell lymphoma cell line P493-6 into NSG mice." (PMID 34399819, 2021). "High-grade B-cell lymphoma with concurrent MYC and BCL2 rearrangements (HGBL-DHL) is a rare, aggressive mature B-cell malignancy with a high likelihood of treatment failure following front-line immunochemotherapies." (PMID 33777762, 2021). "KMT2Ar leukemias, as well as MYC-driven B cell lymphomas, are highly sensitive to inhibition of BCL2 through venetoclax treatment." (PMID 34088716, 2021). "λ-MYC mice, which are of C57BL/6 origin, constitutively express a transgenic c-MYC oncogene in a B-cell-specific manner, which leads to the development of endogenous B-cell lymphomas in 100% of mice." (PMID 33141285, 2021). "The recently revised World Health Organization (WHO) classification of tumors of hematopoietic and lymphoid tissues now acknowledges the new and provisional entity of high-grade B-cell lymphoma, with MYC and BCL2 and/or BCL6 rearrangements (HGBL-DH/TH)." (PMID 33672644, 2021). "DNA-activated protein kinase (DNA-PK) is a PI3K-related kinase capable of phosphorylating MYC at multiple serine residues, promoting its oncogenic activity in MYC-driven B-cell lymphomas." (PMID 34372899, 2021). "In this review, we describe the mechanisms by which MYC attenuates the anti-tumor immune responses in B cell non-Hodgkin lymphomas." (PMID 33092116, 2020). "Through epigenetic regulation and recruiting histone deacetylase 3 (HDAC3), MYC represses miR-15a/miR-16-1 expression in mantle cell and other non-Hodgkin B-cell lymphomas." (PMID 32549409, 2020). "In centroblast B cells and high-grade B cell lymphomas, more H3K27ac signals are at the MYC 3′ downstream region." (PMID 33298918, 2020). "High-grade B-cell lymphoma with rearrangements of MYC and BCL2 and/or BCL6 is an aggressive mature B-cell neoplasm, whereas B-lymphoblastic lymphoma is immature cell proliferation, with a frequent positivity for terminal deoxynucleotidyl transferase." (PMID 32713346, 2020). "Therapeutic study in 30 DLBCL cell lines with various molecular and genetic background found robust cytotoxicity of selinexor, especially in cells with BCL2-rearranged (BCL2-R+) DLBCL or high-grade B-cell lymphoma with MYC/BCL2 double-hit (HGBCL-DH)." (PMID 33148342, 2020). "These transgenic mice develop B-cell lymphomas driven by MYC, whereby PRDM15 can be conditionally deleted at various stages of tumor development." (PMID 32665551, 2020). "B cell lymphoma with dual expression of c-MYC and BCL2 (double-expressor lymphoma, DEL) accounts for approximately one-third of DLBCL cases." (PMID 32695674, 2020).
B-cell lymphoma (continued). "In support of our study, the mutation signature associated with FL was also the characteristic change in high-grade B-cell lymphoma with MYC and BCL2 translocations, and in the EZB or C3 genetic subgroup, which are enriched by BCL2 translocation." (PMID 31844144, 2020). "In the revised fourth edition of the World Health Organization (WHO) classification of lymphoid neoplasms published in 201615, DH/triple-hit (TH) DLBCL was reclassified as high-grade B-cell lymphoma, with MYC and BCL2 and/or BCL6 rearrangements." (PMID 33168821, 2020). "Although MYC is a master regulator involved in the lymphomagenesis of diverse lymphoid tumors, few studies have reported its role in low-grade B-cell NHL." (PMID 32585984, 2020). "In contrast, another study reported that MYC mRNA levels in B cell lymphomas and solid tumors are positively correlated with B7-H6 expression on the tumor cell, a ligand for the NK cell receptor NKp30." (PMID 33092116, 2020). "Subsequent studies revealed that MYC overexpressing B cell NHL cell lines downregulates expression of HLA class I molecules, leading to impaired T cell recognition." (PMID 33092116, 2020). "In hematopoietic malignancies, genomic abnormalities involving the MYC gene are almost always found in B cell lymphomas, but rarely in T cell lymphomas." (PMID 32102485, 2020). "MYC is also under the control of SEs in other types of B cell lymphomas, such as mantle cell lymphoma and LCLs14,57." (PMID 33298918, 2020). "Bcl-w deprivation substantially inhibited MYC-modulated B-cell lymphoma occurrence owing to enhanced MYC-triggered B-cell apoptosis." (PMID 33364236, 2020). "In conclusion, we described a rare EBV-negative high-grade B-cell lymphoma with MYC and BCL2 rearrangements of the male breast." (PMID 33339535, 2020). "The constitutive MYC expression drives an expansion of B cells in the bone marrow which subsequently turns to an overt, aggressive B-cell lymphoma." (PMID 33134177, 2020). "Being initially considered as Burkitt lymphoma, we here rendered the diagnosis of a so-called “high-grade B-cell lymphoma with MYC and BCL2 rearrangements” also called “double-hit lymphoma” with Burkitt morphology." (PMID 33339535, 2020). "In DLBCL cells MYC mediated the repression of miR-34a resulting in a high proliferation of B-cell lymphoma by dysregulation of its target FOXP1." (PMID 32549409, 2020). "Burkitt lymphoma (BL) is a highly aggressive non-Hodgkin B-cell lymphoma characterized by the translocation and deregulation of the MYC (MyeloCytomatosis) gene on chromosome 8." (PMID 33094053, 2020). "This proves that the senescence-inducing cell cycle regulator p21Cip1 was strictly required to prevent the transition of pre-malignant B cells into B-cell lymphomas in ICB-treated λ-MYC mice, and that ICB-mediated p21Cip1 activation was IFN-γ-dependent." (PMID 32165639, 2020). "Patients with MYC overexpressing high grade B cell lymphoma (HGBL) face significant dismal prognosis after treatment with standard immunochemotherapy regimens." (PMID 33092116, 2020). "These lncRNAs were responsive to the inactivation of MYC in BL cell lines, further supporting their relevance for MYC-driven B-cell lymphomas." (PMID 33134177, 2020). "Meanwhile, MYC activation sensitizes MYC/BCL2 double-hit B cell lymphoma cells to inhibition of mitochondrial translation by the antibiotic tigecycline." (PMID 31336613, 2019). "High grade B-cell lymphomas include the entities carrying MYC, BCL2 and/or BCL6 translocations or cases with blastoid morphology without DH translocations." (PMID 31942539, 2019). "In 2017, the World Health Organization (WHO) established a new entity for MYC rearranged DLBCL, called ‘high-grade B-cell lymphoma with MYC and BCL2 and/or BCL6 rearrangements’." (PMID 31028445, 2019).
B-cell lymphoma (continued). "A recent pre-clinical study shows that tigecycline combined with venetoclax promotes the primary response of MYC/BCL2 double-hit B cell lymphoma cells to rituximab-based chemoimmunotherapeutic regimens, also known as R-CHOP." (PMID 31336613, 2019). "Recent studies have suggested that the expression of MYC protein in aggressive B-cell lymphoma can effectively predict a poor prognosis." (PMID 31484540, 2019). "Burkitt lymphoma (BL) is listed in the WHO’s classification of lymphoid tumours as an “aggressive B-cell non-Hodgkin’s lymphoma” characterized by a high degree of proliferation of malignant cells and deregulation of the MYC gene." (PMID 30606206, 2019). "Burkitt lymphoma (BL) is an aggressive B cell lymphoma which originates from the germinal center (GC), and is characterized by oncogenic translocations of the proto-oncogene MYC." (PMID 31557894, 2019). "In hematopoietic malignancies, B-cell lymphomas with up-regulated AID have been shown to carry adverse mutations in genes, such as MYC, PIM1, and PAX5, as well as chromosomal abnormalities, including MYC/IGH rearrangements." (PMID 30679751, 2019). "For prognostication, the most common referral is to exclude MYC rearrangement in the context of DLBCL or High grade B-cell lymphomas." (PMID 30696948, 2019). "BL is a highly aggressive B-cell NHL characterized by the translocation and dysregulation of c-MYC on chromosome 8." (PMID 31484540, 2019). "MYC acts as a proto-oncogene and plays an important role in hematologic cancers such as aggressive B cell lymphoma as well as in a number of solid tumors." (PMID 31288832, 2019). "MYC/BCL double-hit lymphomas (DHL) are high-grade B cell lymphomas with MYC and BCL2 or BCL6 translocations." (PMID 31336613, 2019). "High grade B cell lymphoma with DH/TH (i.e. concurrent translocations of MYC and BCL2, and/or BCL6) has an adverse prognosis (Grade 2B)." (PMID 30190794, 2018). "The identification and role of MYC-regulated miRNAs was performed in MYC-inducible cell lines models of B-cell lymphoma." (PMID 30038718, 2018). "Considering these cytogenetics findings in the context of the revised 2017 WHO classification system, the DLBCL component should be designated “high-grade B-cell lymphoma with MYC and BCL2 rearrangements”." (PMID 29793519, 2018). "Although double‐hit or triple‐hit B‐cell lymphomas are well‐known with worse prognosis, previous studies concerning the prognostic impact of a c‐MYC rearrangement alone have been controversial." (PMID 29473332, 2018). "Emerging B cell lymphomas are characterized by high MYC levels and this model is widely used to study the mechanisms of MYC-driven lymphomagenesis." (PMID 29741575, 2018). "In the light of the newly shaped entity of high-grade B-Cell lymphoma with MYC, BCL2 and or BCL6 aberrations, which was excluded from the current study, however, this was to be expected." (PMID 29731969, 2018). "In summary, we present a novel “double hit” high-grade B-cell lymphoma cell line, designated DH-My6, with concurrent MYC/IGH and BCL6/IGH rearrangements." (PMID 30323893, 2018). "Recently, miRNA-494 was reported to be a part of a regulatory loop between EZH2 and c-MYC in B-cell lymphoma." (PMID 28052011, 2017). "In hematopoietic malignancies, genomic abnormalities involving the c-MYC gene are almost always seen in B-cell lymphomas." (PMID 28379189, 2017). "The WHO Classification of Tumours of Haematopoietic and Lymphoid Tissues published in 2008, included three types of B cell lymphomas where MYC dysregulation was one of the most important aberrations influencing clinical behavior: BL, DLBCL, and BCLU." (PMID 28375188, 2017). "The transgenic murine model Eμ-MYC features MYC gene insertion into the IgH locus with a 100% incidence of B-cell lymphoma developing." (PMID 28265553, 2017).
B-cell lymphoma (continued). "DHL typically refers to both DHL and THL, and are currently classified as high-grade B-cell lymphoma, with MYC and BCL2 and/or BCL6 rearrangements in the 2016 revision of the WHO classification of lymphoid neoplasms." (PMID 28379189, 2017). "To interrogate if this phenomenon was restricted only to MYC-driven B cell lymphomas, we also explored a model of IR-induced thymic lymphomagenesis." (PMID 29167438, 2017). "In P493-6 cells MYC induces a transcriptional program resembling that of Burkitt lymphoma (BL), a B-cell lymphoma characterized by the activating translocation of the MYC gene." (PMID 28704924, 2017). "This group of authors recognized DHL and THL as clinical and pathological categories, designated high-grade B-cell lymphomas (HGBL) with MYC and BCL2 and/or BCL6 rearrangements." (PMID 28061782, 2017). "Subsequent studies demonstrated that the c-MYC gene, coupled with the immunoglobulin μ or κ enhancer in transgenic mice, was highly leukemogenic and resulted in the development of fatal B-cell lymphomas." (PMID 28379189, 2017). "c-MYC rearrangement is the most extensively studied, and B-cell lymphomas with c-MYC rearrangements show a spectrum of clinical course ranging from indolent low-grade B-cell lymphoma to the highly aggressive DHL." (PMID 28379189, 2017). "In aggressive B-cell NHL, the importance of MYC and BCL2 proto-oncogene coexpression (as assessed by immunohistochemistry) and high-grade histologic features are particularly noteworthy." (PMID 28321348, 2017). "CHK1 inhibitors have shown promising results in killing transplanted MYC-driven mouse B cell lymphomas in mice and Burkitt lymphoma cell lines in vitro." (PMID 29167438, 2017). "The detection of c-MYC gene translocation and c-MYC protein expression has become essential in the clinical diagnosis and prognosis of aggressive B-cell lymphomas." (PMID 28379189, 2017). "This notion is further supported by the observation that MYC-induced B-cell lymphomas dramatically reduced the time of latency at either a DMTF1(−/−) or DMTF1(+/−) genetic background." (PMID 28257090, 2017). "Translocation of the MYC oncogene to a site downstream of a B-cell specific enhancer or promoter region results in B-cell lymphoma." (PMID 28265553, 2017). "c-MYC overexpression suppresses antigen presentation through the human leukocyte antigen (HLA) class II pathway in BL and likely other B-cell lymphomas." (PMID 28379189, 2017). "This review summarizes the role of c-MYC in B-cell lymphomas and leukemias, particularly in relation to the specific subtypes classified under the 2016 revision of the World Health Organization (WHO) classification of lymphoid neoplasms." (PMID 28379189, 2017). "In B-cell lymphomas, the MYC gene is subject to chromosomal rearrangements that result in MYC overexpression." (PMID 28704924, 2017). "According to the 2016 WHO classification revision, patients with DH translocations should be excluded from the DLBCL NOS category and placed within the novel category “High-grade B-cell lymphomas, with MYC and BCL2 or BCL6 translocations”." (PMID 29088292, 2017). "Conversely, c-MYC rearrangement is rare in low-grade B-cell lymphomas, and is most commonly observed in FL and CLL/SLL." (PMID 28379189, 2017). "Dysregulation of c-MYC is essential in the pathogenesis of a number of B-cell lymphomas, but is rarely reported in T-cell lymphomas." (PMID 28379189, 2017). "Taken together, these findings suggest that MYC (over)expression in B cell lymphomas is an event that promotes tumor survival and aggressiveness of the disease through a complex interplay of different signaling pathways." (PMID 28375188, 2017). "A recent work using a mouse model has demonstrated the critical need of PI3K pathway activation besides MYC deregulation for the malignant transformation of normal B cells in BL, an aggressive B-cell lymphoma with an extremely high proliferation index." (PMID 29245936, 2017).